EWSR1 (EWS RNA binding protein 1)
Diseases named in the same sentence as EWSR1 in open-access papers (continued):
Sharing a sentence is not in itself a finding about the gene and the disease.
sarcoma (continued). "Although these sarcomas have variable cell phenotypes, transcriptomes, prevalence, and prognoses, they are all driven by FUS, EWSR1, or TAF15 (sometimes referred to as the ‘FET’ gene family) fused to a transcription factor." (PMID 33669307, 2021). "FUS and EWSR1 belong to the FET group of fusion oncogenes, found primarily in sarcomas and leukemias." (PMID 34068344, 2021). "Genetically and clinically different round cell sarcomas were recently identified: round cell sarcoma with EWSR1-non ETS (NFATC2 and PATZ1 being the most common ones), CIC-rearranged sarcomas and sarcomas with BCOR genetic alteration." (PMID 34514574, 2021). "No discernable difference in mTOR pathway activation was identified between EWSR1-ETS and CIC-DUX4 positive sarcomas (EWSR1-ETS vs. CIC-DUX4: z-score = −0.2, p = 0.01)." (PMID 34021224, 2021). "Although a positive result is highly sensitive for EwS, some morphological mimics can exhibit break-apart events in the EWSR1 gene (e.g., DSRCT, AFH, and EWSR1-NFATc2-positive sarcomas)." (PMID 32164354, 2020). "Although CIC-rearranged sarcomas are conventionally referred to as “Ewing-like sarcomas”, recent studies have described a significant distinction between CIC-rearranged sarcomas and EWSR1-rearranged Ewing sarcomas." (PMID 31676869, 2019). "The FET-protein family comprises FUS (fused in sarcoma, and also abbreviated TLS (translocated in liposarcoma)), EWS (Ewing sarcoma breakpoint region 1, and also abbreviated EWSR1) and TAF15 (TATA box binding protein associated factor 68 kDa)." (PMID 26573619, 2015). "The last group of hnRNPs found in maintenance of stem cell self-renewal and development potency is RNA binding protein EWS (Ewing sarcoma breakpoint 1, also called EWSR1) and FUS (fused in sarcoma, also called TLS/hnRNP P2)." (PMID 23984388, 2013). "Interphase FISH analysis for rearrangement of the EWSR1 and FUS loci was successfully performed in two of the three cases of myoepithelioma-like sarcoma." (PMID 22588017, 2011). "The Ewing sarcoma breakpoint region 1 gene (EWSR1), also known as EWS, is fused to a number of different partner genes as a result of chromosomal translocation in diverse sarcomas." (PMID 17912356, 2007). "We established a novel sarcoma cell line, PF1095, with a EWSR1::POU2AF3 fusion." (PMID 40134582, 2025). "Nine fusion genes were specific to particular histotypes, including SYT::SSX fusion in synovial sarcoma, EWSR1::FLI1 fusion in ES, EWSR1::NR4A3 fusion in EMC, BCOR::CCNB3 fusion in sarcoma with BCOR genetic alterations, and EWSR1::CREB3L1 fusion in sclerosing epithelioid fibrosarcoma." (PMID 40755265, 2025). "In the 5th edition, the WHO classification of soft tissue and bone tumors CIC-fused sarcomas, BCOR-rearranged sarcomas, and round cell sarcomas with EWSR1::non-ETS fusion are distinguished." (PMID 40134582, 2025). "CIC-rearranged sarcomas, the most frequent among EWSR1-negative SRCSs, show a strong soft-tissue predilection and significantly worse survival than ES." (PMID 41514642, 2025). "The differential diagnosis for such a localization is mainly with EXING sarcoma, so it is important to have pathohistological examination for MyoD1(which confirms RMS), CD 99 and EWSR1 gene evaluation (which could confirm EWING sarcoma)." (PMID 39767925, 2024). "Among the 30 cases with follow-up results, including the four cases reported in our study, the mortality rate of EWSR1/FUS::NFATC2 sarcoma is not high, even though it can exhibit local recurrence and lung metastasis." (PMID 38254207, 2024). "The poor response to therapy is largely attributed to genetic abnormalities within the sarcoma cells, including EWSR1::non-ETS fusions, BCOR genet alterations, and EWSR1::ETS fusions." (PMID 39682287, 2024). "Recent studies have highlighted a variety of sarcomas harboring EWSR1 gene rearrangements fused to non-ETS family of transcription factors." (PMID 39031200, 2024).
sarcoma (continued). "The most common representative of these non-ETS GF entities is EWSR1::NFATC2 or FUS::NTAC2 sarcoma, followed by EWSR1::PATZ1 sarcoma." (PMID 38339014, 2024). "Among them, three distinct sarcoma subtypes with specific clinical, pathological, and molecular features have been individualized in the last WHO classification, including CIC‐rearranged sarcoma (CIC‐RS), BCOR‐rearranged sarcoma, and SRBCS with EWSR1‐non ETS fusion." (PMID 36537582, 2023). "The incidence of sarcoma with EWSR1::non-ETS fusions accounted for 6% of the 240 patients in a recently analyzed large cohort of patients with round cell sarcomas with EWSR1 or FUS fusions." (PMID 36115869, 2022). "Among these, protein capicua homolog (CIC)- and B-cell lymphoma 6 corepressor (BCOR)-rearranged sarcomas along with sarcomas carrying Ewing sarcoma breakpoint region 1 (EWSR1)-non-erythroblast transformation specific (ETS) fusions feature most prominently." (PMID 36158667, 2022). "Fourteen subjects with EWSR1-NFATc2 fusion positive sarcoma were identified in the Foundation Medicine FoundationCore® (FMI) research database from a total of 1024 EWSR1 fusions, resulting in an overall prevalence of 1.4% among EWSR1 fusion positive sarcomas." (PMID 34021224, 2021). "The Fluorescence in-situ Hybridization (FISH) for Ewing's Sarcoma (EWS), 22q12 (EWSR1) rearrangement was negative and his bilateral bone marrow biopsy report was negative for malignant cells." (PMID 35199700, 2021). "This group of tumors can be subdivided into capicua transcriptional repressor (CIC)-rearranged sarcomas, Bcl6 corepressor (BCOR)-rearranged sarcomas, sarcomas with EWSR1 fusion to non-ETS family members, and unclassified round-cell sarcomas." (PMID 34068344, 2021). "BCOR-CCNB3 sarcomas (BCS) were first identified in 2012 from a series of undifferentiated round cell sarcomas lacking known genetic alterations such as EWSR1 gene rearrangement." (PMID 34103053, 2021). "The remaining 15 cases of EWSR1 gene rearrangement- negative undifferentiated small round cell sarcomas (included 2 CIC rearrangement sarcomas and 13 undifferentiated small round cell sarcomas) were negative for BCOR gene rearrangement." (PMID 34103053, 2021). "It is likely that some of the trials in our report may have included patients with sarcomas with alternative transcripts to the usual EWS‐FLi1 (e.g., CIC or BCOR) instead of the EWSR1 translocations." (PMID 33452711, 2021). "CIC-rearranged sarcomas constitute 60% of round-cell sarcomas lacking EWSR1 rearrangement while BCOR sarcomas constitute only 4%." (PMID 34722090, 2021). "EWSR1 gene has been identified as a partner in a wide variety of clinically and pathologically diverse sarcomas as well as some nonmesenchymal tumours." (PMID 32675940, 2020). "In addition 100% concordance was achieved overall for the sarcoma panel containing SYT (SS18), EWSR1 and FOXO1 in the UK NEQAS International Quality Expertise 2017 evaluation." (PMID 31236139, 2019). "Our optimized method achieved 100% concordance for the HER2 FISH NordiQC - Quality Control 2015 evaluation, 100% concordance for genotyping and clerical accuracy for the sarcoma panel containing CHOP (DDIT3), FUS, EWSR1 and MDM2 in the UK NEQAS International Quality Expertise 2016 evaluation." (PMID 31236139, 2019). "The subgroup of myoepithelioma-like sarcomas was further investigated with regard to the status of the EWSR1 and FUS loci; however, no rearrangement was found." (PMID 22588017, 2011). "Therefore, although EWSR1/FUS::NFATC2 sarcoma has a relatively specific FISH presentation, when diagnosing tumors with EWSR1/FUS::NFATC2 gene rearrangement, it is necessary to consider factors such as the clinical presentation, histological changes, treatment and prognosis." (PMID 38254207, 2024). "Rare BCOR sarcoma was described in a group of small round cell bone tumors lacking the canonical EWSR1 translocation: only 24 BCOR::CCNB3 positive tumors could be identified in an analysis of 594 sarcoma." (PMID 37212486, 2023).
sarcoma (continued). "Recurrent alterations identified were often unique to specific sarcoma subtypes; CDK4/MDM2 amplifications were identified in all but one dedifferentiated liposarcoma, ASPSCR1-TFE3 fusions in all patients with alveolar soft part sarcoma, and fusions involving EWSR1 in all patients with SBRCT." (PMID 35710741, 2022). "In the present study, only two of the cases diagnosed as myoepithelial-like sarcomas could be analyzed by FISH for EWSR1-rearrangement, and both were negative." (PMID 22588017, 2011). "These groups have been categorized as the round cell sarcomas associated with fusion forming EWSR1 (non-ETS fusions), the CIC (Capicua Transcriptional Repressor) rearrangement associated sarcomas, and BCOR (BCL-6 transcriptional co-repressor) associated sarcomas." (PMID 38954213, 2025). "Additionally, the EWSR1/FUS::NFATC2 gene rearrangement feature can also be detected in simple bone cysts, but it does not harbour the amplification of the fusion gene and exhibits different clinical manifestations, histology, and prognosis compared to EWSR1/FUS::NFATC2 sarcoma." (PMID 38254207, 2024). "The latest World Health Organization classification of soft tissue and bone tumors recognizes 4 categories within this group: ES, round cell sarcoma with EWSR1-non-ETS fusions, CIC-rearranged sarcoma, and sarcoma with BCOR alterations." (PMID 40948502, 2025). "The most recent WHO Classification of Soft Tissue and Bone Tumors recognizes four categories within this group: ES, round cell sarcoma with EWSR1-non-ETS fusions, CIC rearranged sarcoma, and sarcoma with BCOR alterations." (PMID 40948512, 2025). "The differential diagnosis includes tumors with small round-cell morphology, mainly round cell sarcoma with EWSR1 non-ETS fusion, CIC-rearranged sarcoma, and sarcoma with a BCOR genetic alteration." (PMID 39158802, 2025). "In this study, they included CIC::DUX4, BCOR-altered, EWSR1::ATF1/CREB1, and YWHAE::NUTM2B sarcomas, as well as fusion-negative SRCSs, reflecting the expanding molecular landscape within this spectrum." (PMID 41514642, 2025). "These are further subdivided into three entities: CIC-rearranged sarcoma, round cell sarcoma with EWSR1::non-ETS fusions, and sarcoma with BCOR genetic alterations." (PMID 40841513, 2025). "Currently, three categories are acknowledged: round cell sarcomas with EWSR1 gene fusion with non-ETS family members, CIC-rearranged sarcomas, and BCOR-rearranged sarcomas." (PMID 37720343, 2023). "A diagnosis of relapsed undifferentiated sarcoma was refined to BCOR-sarcoma due to the identification of the BCOR-CCNB3 fusion and absent EWSR1 fusion." (PMID 36182817, 2022). "EWSR1 FISH revealed tumor cells with break-apart signal without amplification in one complex cystic lesion and EWSR1 amplification in both sarcomas was documented." (PMID 36555836, 2022). "The latest 2020 WHO Classification of Tumors of Soft Tissue and Bone includes four categories for round cell sarcomas: EwS; round cell sarcoma with EWSR1::non-ETS fusions; CIC-rearranged sarcomas; and sarcomas with BCOR gene alterations." (PMID 36115869, 2022). "Case 10 tested negative for ES and Ewing-like tumours (CIC sarcoma and NFATC2-reaarranget tumour), but targeted NGS revealed a fusion between EWSR1 and ATF1." (PMID 36614077, 2022). "The histology and immunoprofile of EWSR1:PATZ1-fused sarcoma has also been described as incredibly polyphenotypic, but MN1:PATZ1-fused sarcomas have not yet been described." (PMID 34417833, 2021). "These include sarcomas with BCOR alterations, CIC-rearranged sarcoma (see ‘WT1 and ETV4’), and round cell sarcoma with EWSR1-non-ETS fusions." (PMID 33921435, 2021). "CIC-rearranged sarcomas constitute a significant portion of round-cell sarcomas lacking EWSR1 rearrangement (60%), whereas BCOR sarcomas only constitute a much smaller portion (4%)." (PMID 33801953, 2021).
sarcoma (continued). "However, our case showed positive CIC and negative EWSR-1 gene rearrangements by FISH, confirming the diagnosis of CIC-rearranged sarcoma." (PMID 40722508, 2025). "These tumors comprise a heterogeneous category of old and new or emerging entities including morphologically defined sarcomas/neoplasms with EWSR1::CREB fusions and unclassified sarcomas with non-ETS EWSR1 fusions such as EWSR1::PATZ1 and EWSR1::NFATC2 fusions." (PMID 39031200, 2024). "We report five patients with EWSR1/FUS::NFATC2-rearranged neoplasms, including one simple bone cyst (SBC), two complex cystic bone lesions lacking morphological characteristics of SBC, and two sarcomas." (PMID 36555836, 2022). "Rather, these assays detect EWSR1 rearrangements, which is important for differential diagnosis with other sarcoma subtypes that harbor EWSR1 fusions with non-ETS genes (e.g., desmoplastic small round cell tumors (DSRCTs), or EWSR1-NFATc2-translocated sarcomas)." (PMID 33919988, 2021). "Similar to the EWSR1 round cell sarcoma with non-ETS partners subset of fusions, this may be because CIC and BCOR sarcomas are rare and would not be picked up using morphology, immunohistochemistry, or EWSR1 break-apart FISH." (PMID 33488267, 2020).
clear cell sarcoma (57 papers, 2003 to 2026). A rare malignant neoplasm with melanocytic differentiation characterized by the presence of polygonal or spindle shaped clear cells. "Our results showed that the frequency of abnormal signal patterns of EWSR1 in clear cell sarcoma is very low (2%, 1/61), which is consistent with a previous report." (PMID 40666501, 2025). "All the cases presented received a histopathological diagnosis of clear cell sarcoma and molecular confirmation of the presence of the typical transcription gene (EWSR1/XX)." (PMID 40310428, 2025). "As an example, Mivebresib treatment was shown to reduce the protein and mRNA levels of EWSR1::ATF1 in a dose-dependent manner in clear cell sarcoma, due to the modulation of BRD4 recruitment at the EWSR1 promoter region." (PMID 41166819, 2025). "Detection of EWSR1 gene rearrangement and/or confirmation of an EWSR1::ATF1 or EWSR1::CREB1 gene fusion confirms the diagnosis of clear cell sarcoma." (PMID 39264472, 2024). "In contrast, similar to EWSR1::ATF1 fusion in clear cell sarcoma, both CRTC1::TRIM11 and MITF::CREM fusions likely lead to MITF overexpression through the induction of the CREB signaling cascade." (PMID 39264472, 2024). "The gene fusion of activating transcription factor 1 (ATF1) and the Ewing sarcoma breakpoint region 1 (EWSR1) are pathognomonic for clear cell sarcoma, representing the key to the diagnosis." (PMID 38929464, 2024). "The relationship between cellular histogenesis and molecular phenotypes for the EWSR1- ATF1 fusion in clear cell sarcoma (CCS) requires further characterization." (PMID 35477713, 2022). "Clear cell sarcoma (CCSA) is characterized by a chromosomal translocation leading to EWSR1 rearrangement, resulting in aberrant transcription of multiple genes, including MET." (PMID 34885165, 2021). "For instance, EWSR1 or FUS can fuse to ATF1 or CREB1 in clear cell sarcoma of soft tissue as well as angiomatoid fibrous histiocytoma." (PMID 34081036, 2021). "Clear cell sarcoma (CCSA) is a rare subtype of soft tissue sarcoma characterized by EWSR1 rearrangement and subsequent MET upregulation." (PMID 34885165, 2021). "In seven, analysis for EWSR1-CREB1 and EWSR1-ATF1 fusion transcripts or EWSR1 gene rearrangement was performed to exclude clear cell sarcoma (CCS)." (PMID 33061792, 2020). "Fluorescence in situ hybridization showed a rearrangement of the EWSR1 gene on chromosome 22q12, which led to a diagnosis of primary clear cell sarcoma in the skin." (PMID 29072181, 2018). "Because the treatments for clear cell sarcoma and conventional melanoma are different, fluorescence in situ hybridization for EWSR1 should be performed in any dermal lesions with melanocytic features that do not have an in situ component." (PMID 29072181, 2018). "and for assessment of EWSR1 gene rearrangement (for diagnosis of a variety of tumours, such as clear cell sarcoma)." (PMID 25165418, 2014). "Although recurrent EWSR1::ATF1 fusions were initially limited to a triad of mesenchymal neoplasms including clear cell sarcoma of soft tissue, angiomatoid fibrous histiocytoma and malignant gastrointestinal neuroectodermal tumor (MGNET), this family has been expanding." (PMID 39031200, 2024). "The observation that EWSR1::ATF1-positive clear cell sarcomas show consistent melanocytic differentiation and expression of the melanocytic-specific MITF (MITF-M) transcript fueled the idea of the EWSR1::ATF1 fusion protein-mediated transactivation of the MITF promoter." (PMID 39769457, 2024). "This study reveals the epigenetic and transcriptional suppression mechanism of the fusion oncogene EWSR1::ATF1 in clear cell sarcoma by histone deacetylase inhibitor treatment as well as identifying SOX10 as a transcription factor that regulates EWSR1::ATF1 expression." (PMID 37405123, 2023).